ACSM5 (acyl-CoA synthetase medium chain family member 5)
Description:
Acyl-CoA synthetase that catalyzes the ATP-dependent activation of fatty acids to their corresponding acyl-CoA thioesters, the first committed step in fatty acid metabolism (By similarity). Negatively regulates lipid accumulation via inhibition of FABP4-PPARgamma signaling.
Synonyms: FLJ20581
Tractability: PROTAC: its protein half-life has been measured.
Gene: Protein-coding gene on chromosome 16 (20,409,308 to 20,441,337, forward strand). Ensembl gene ENSG00000183549.
Subcellular location: Mitochondrion matrix
Subcellular location (Human Protein Atlas): Vesicles
Pathways (Reactome):
Drug ADME: Aspirin ADME
Metabolism: Conjugation of salicylate with glycine
Gene Ontology:
Molecular function: fatty acid ligase activity; fatty-acyl-CoA synthase activity; CoA-ligase activity; medium-chain fatty acid-CoA ligase activity
Biological process: acyl-CoA metabolic process; fatty acid biosynthetic process
Cellular component: mitochondrion; mitochondrial matrix
Genetic constraint (gnomAD): Loss-of-function variants: 55 observed, 68.62 expected, observed/expected ratio (o/e) 0.8, 90% interval 0.64 to 1. The upper end of that interval is the gene's LOEUF score, 1, which puts it in group 4 of 6, group 1 being the genes least tolerant of losing a copy. Missense variants: 714 observed, 724.96 expected, observed/expected ratio (o/e) 0.98, 90% interval 0.93 to 1.05. Synonymous variants: 285 observed, 282.53 expected, observed/expected ratio (o/e) 1.01, 90% interval 0.92 to 1.11.
Homologues: Orthologues: macaque ACSM5 (97% identical), chimpanzee ACSM5 (90% identical), pig ACSM5 (89% identical), mouse Acsm5 (86% identical), rabbit ACSM5 (86% identical), dog ACSM5 (86% identical), guinea pig ACSM5 (85% identical), rat Acsm5 (80% identical), tropical clawed frog acss2.2 (28% identical), zebrafish acss2l (26% identical), Caenorhabditis elegans acs-2 (19% identical), Caenorhabditis elegans acs-1 (18% identical). Paralogues in human: ACSM4 (61% identical), ACSM3 (58% identical), ACSM1 (55% identical), ACSM2A (54% identical), ACSM2B (53% identical), ACSM6 (36% identical), ACSS2 (28% identical), ACSS1 (27% identical), ACSS3 (24% identical), ACSF2 (21% identical), ACSF3 (20% identical), AACS (20% identical), and 1 more.
Diseases named in the same sentence as ACSM5 in open-access papers:
ACSM5 is named in the same sentence as 10 diseases in open-access papers, as found by Europe PMC text mining. Sharing a sentence is not in itself a finding about the gene and the disease. The quoted sentences say what the papers report.
breast carcinoma (2 papers, 2021 to 2025). "For example, studies have shown that ACSM5 is low expressed in tumor tissues of breast cancer and lung cancer and its expression level is related to the poor prognosis of patients, which can be used as a potential marker for disease prognosis and diagnosis." (PMID 34593020, 2021). "ACSM5, a member of the Acyl-CoA Synthetase (ACS) enzyme family, was previously identified via TCGA data as a significant breast cancer biomarker, with reduced expression in malignant tissues." (PMID 40109861, 2025).
lung adenocarcinoma (2 papers, 2022 to 2026). A carcinoma that arises from the lung and is characterized by the presence of malignant glandular epithelial cells. "A previous study reported that ACSM5 was identified as a biomarker for lung adenocarcinoma prognosis and was also associated with the tumor microenvironment." (PMID 36054420, 2022).
thyroid cancer (2 papers, 2023 to 2024). "For example, a SNP in acyl‐CoA synthetase medium chain family member 5 (ACSM5), a candidate gene for thyroid cancer, reduces m6A modification and ACSM5 expression in thyroid cancer tissues, and is associated with the poor prognosis." (PMID 38769304, 2024). "ACSM1 and ACSM5 have been reported to be associated with the progression of prostate and thyroid cancers, respectively." (PMID 37426827, 2023).
tumor (4 papers, 2020 to 2025). "The expression of ACSM5 has been previously linked to tumor aggressiveness and poor prognosis, and its role in fatty acid metabolism suggests it may contribute to tumor energy homeostasis and survival." (PMID 40519938, 2025). "Following LASSO Cox regression analysis, heat shock protein B2 (HSPB2) and acyl-CoA synthetase medium-chain family member 5 (ACSM5) were identified as the most significant genes associated with tumor microenvironment (TME) alterations and Helicobacter pylori infection." (PMID 40519938, 2025). "The role of ACSM5 in tumor progression is still in the initial stage of research and is worthy of further exploration." (PMID 33102522, 2020). "However, the detailed roles and specific mechanisms of ACSM5 in tumor progression need further exploration." (PMID 36054420, 2022).
infection (1 paper, 2025). The state of being infected such as from the introduction of a foreign agent such as serum, vaccine, antigenic substance or organism. "In this study, we first observed elevated expression levels of ACSM5 and HSPB2 in Helicobacter pylori-positive GC patients compared to those without the infection." (PMID 40519938, 2025).
ACSM5 also shares sentences with these, for which no sentence is quoted: attention deficit-hyperactivity disorder (1 paper); chronic kidney disease (1); dementia (1); lung carcinoma (1); myocardial infarction (1).